AHR (aryl hydrocarbon receptor)
Diseases named in the same sentence as AHR in open-access papers (continued):
Sharing a sentence is not in itself a finding about the gene and the disease.
Hepatic steatosis (continued). "Recently, multiple research groups have utilized a plethora of in vitro and in vivo models that mimic NAFLD pathology to investigate the functional significance of AhR in fatty liver disease." (PMID 37284280, 2023). "In conclusion, chronic treatment with AN1284 (1mg/kg/day) reduced pre-existing steatosis and fibrosis through AhR, which affects several contributors to the development of fatty liver disease." (PMID 37664863, 2023). "2,3,7,8-Tetrachlorodibenzo-p-dioxin (TCDD), a potent AhR agonist, induces hepatic steatosis and metabolic dysfunction." (PMID 36077780, 2022). "Specific gestational deletion of AhR from liver exacerbates metabolic disease conditions, such as hepatic steatosis, under HFD, whereas CKO from adult liver helps ameliorate the pathology." (PMID 35887027, 2022). "Constitutive activation of AHR induced spontaneous hepatic steatosis, which was dependent on the increased expression of fatty acid translocase and fatty acid transport proteins." (PMID 36139083, 2022). "In this study, we aimed to investigate the role of indole-3-acetic acid (IAA) and AHR in sulforaphane (SFN) alleviates hepatic steatosis in mice fed on a high-fat diet (HFD)." (PMID 34722615, 2021). "To investigate the relationship between the expression of AHR and fatty acid oxidation in hepatic steatosis induced by GHR deletion, we examined the expression of genes related to fatty acid oxidation." (PMID 34803486, 2021). "Administration of an AhR agonist to mice has also been reported to improve alcohol-induced liver injury and can defend against gut inflammation and relieve hepatic steatosis in obesity and NAFLD." (PMID 34944732, 2021). "Our results established AHR as a modulator of hepatic steatosis, thereby providing a therapeutic target for lipid metabolism disorder." (PMID 34803486, 2021). "Activation of the aryl hydrocarbon receptor (AhR) leads to fatty liver diseases in animal models and in humans." (PMID 35822025, 2021). "By contrast, the AhR protects against hepatic steatosis induced by a HFD and subsequent lipotoxicity." (PMID 31638212, 2019). "Similar to the previously observed protective role for AhR against hepatic steatosis and hepatic inflammation in HFD mice, indigo supplementation decreased liver triglyceride content and hepatic inflammation by increasing IL-10 and M2-like macrophages." (PMID 30944419, 2019). "Activation of AhR protects against fatty liver induced by insulin resistance by activating fibroblast growth factor 21 (FGF21) to regulate lipid and energy metabolism in such mice." (PMID 31638212, 2019). "Previous studies show that AhR as well as PXR induces liver steatosis through induction of CD36, a fatty acid transporter." (PMID 31681434, 2019). "In the present study, we find that AhR promotes liver steatosis in diet-induced obese mice through a different pathway by directly inducing Pemt, which results in an increase in the ratio of PC/PE." (PMID 29416063, 2018). "Dysregulation of lipid metabolism leading to hepatic steatosis and insulin resistance suggests that the AHR plays an important role in integrating exogenous and endogenous influences in lipid and energy metabolism." (PMID 27858116, 2017). "And activating hepatic AhR signaling led to liver steatosis." (PMID 39979552, 2025). "Furthermore, modulation of nuclear receptors such as AHR, FFAR2, FXR, and TGR5 links metabolic-associated fatty liver disease, COVID-19, and oxidative stress." (PMID 41415278, 2025). "Furthermore, some PAHs and/or dioxins can activate molecular pathways towards hepatic steatosis by binding to the AhR in the liver." (PMID 38674815, 2024). "Furthermore, TDO2 shifted macrophage towards M1 polarization via activation of KYN/AHR/NF‐κB signaling pathway, thus accelerating hepatic steatosis." (PMID 39364706, 2024).
Hepatic steatosis (continued). "A subset of these contaminants possesses lateral chlorines that induce a diverse spectrum of aryl hydrocarbon receptor (AHR)-mediated species-, sex-, tissue-, cell- and promoter-specific responses including the dose-dependent progression of hepatic steatosis to steatohepatitis with fibrosis." (PMID 36914879, 2023). "Thus far, studies suggest that AhR is a ‘double-edged sword’ within the context of the fatty liver disease." (PMID 37284280, 2023). "Moreover, the role of AhR in fatty liver disease has been controversial due to both beneficial and adverse effects on liver pathology." (PMID 37284280, 2023). "For non-EATS modalities, qAOPs concerning immunosuppression and decreased egg production in fish because of GR signaling have been developed, as well as early life stage mortality in birds and fishes via AhR, and liver steatosis in humans via PPARα, among others." (PMID 34418449, 2022). "However, pioneering studies using Xenopus tropicalis demonstrated the capacity of benzo[a]pyrene (50 ng/L) at inducing liver steatosis and metabolism impairments in frogs, suggesting that AHR-regulation of metabolic pathways are conserved among species." (PMID 34418449, 2022). "In this context, it has been reported that mice expressing a high constitutively active form of AhR spontaneously developed hepatic steatosis, characterized by high amounts of fatty acid import, suppressed fatty acid oxidation, and increased oxidation and mobilization of peripheral fat storage." (PMID 36418969, 2022). "Thus, AHR in hepatocytes is a critical factor in the initiation of hepatic steatosis and a potential molecular target for intervention." (PMID 34803486, 2021). "H-Exo PC-induced AhR signaling activation contributes to the development of insulin resistance, but constitutive expression of AhR in AhR transgenic mice has been shown to improve insulin sensitivity, despite exacerbating hepatic steatosis by induction of FGF2151." (PMID 33431899, 2021). "In a study using mice with constitutive expression of human AHR specifically in the liver, fibroblast growth factor 21 (FGF21) could be identified as a direct AHR target and a major mediator of both hepatic steatosis and systemic insulin hypersensitivity." (PMID 34075438, 2021). "To explore whether the protective effects of GHR are dependent on AHR in hepatic steatosis, we carried out the rescue experiments on siGHR human hepatocytes." (PMID 34803486, 2021). "The predicted activation of AHR by SPI feeding in this study could be part of the explanation for the observed amelioration of liver steatosis in SPI-fed obese rats compared with CAS-diet-fed rats." (PMID 34262928, 2021). "A synthetic pelargonidin (Mt-P) transactivates AhR, and has been shown, in HFD-fed C57BL/6J mice, to attenuate body weight gain, intestinal and liver inflammation, and ameliorate insulin sensitivity, while worsening liver steatosis, of which were abrogated by gene ablation of AhR." (PMID 33603741, 2020). "The AhR protects against fatty liver induced by insulin resistance by activating FGF21." (PMID 31638212, 2019). "Specifically, AhR sustained activation results in induction of fatty acid transport proteins and enhanced lipid uptake via activity of the fatty acid transporter CD36 to eventually cause accumulation of triglycerides leading to hepatic steatosis." (PMID 27045805, 2016). "However, protective effects of AHR in hepatic steatosis have also been suggested." (PMID 34075438, 2021). "ARNT may down-regulate fatty liver disease induction by the aryl hydrocarbon receptor." (PMID 31800592, 2019). "Thus, we tested whether expression of AhR contributes to the development of fatty liver in mice fed a high-fat/high fructose (HF/HF) diet and further tested whether co-expression of SHP or downregulation of Pemt attenuates the development." (PMID 29416063, 2018).
Hepatic steatosis (continued). "Microbial tryptophan metabolites are well-known activators of AhR, particularly in the gut, where AhR activation enhances the intestinal barrier function and stimulates GLP-1 secretion, leading to improved glucose metabolism and hepatic steatosis." (PMID 39941095, 2025). "And we also confirmed that I3C improved liver steatosis and increased liver ILC1 frequency induced by HFD were notably abolished by CH-221391, a potent AhR antagonist." (PMID 40046764, 2025). "BAs bind to TGR5 to increase AHR expression and promote transcription of ACOX 1 and CPT 1 A by triggering CAMP-ERK pathway and inhibit NLRP3 activity by triggering CAMP-PKA pathway, while AHR also inhibit activation of NLRP3, thus inhibiting hepatic steatosis." (PMID 39944639, 2025). "Notably, the liver-specific knockout of AhR not only mitigated hepatic steatosis but also attenuated adipocyte hypertrophy and macrophage infiltration in adipose tissues, suggesting that systemic lipid metabolism dysregulation is mediated by hepatic AhR activation." (PMID 40943373, 2025). "Liver-specific knock-out AHR mice showed increased DNL activity, severe hepatic steatosis, inflammatory response and liver injury." (PMID 39426289, 2024). "In contrast, adult AhR CKO from all types of adipose tissue protected males and females gained significantly less weight and were protected from hepatic steatosis when fed HFD." (PMID 35887027, 2022). "Emerging evidence has shown the importance of the aryl hydrocarbon receptor (AHR) in liver diseases such as alcoholic liver disease, fatty liver disease, and liver failure." (PMID 36139083, 2022). "Activation of AHR can induce CD36 expression, enhance fatty acid uptake, and lead to hepatic steatosis." (PMID 34803486, 2021). "However, the administration of endogenous agonists of AhR such as cinnabarinic acid (CA) down-regulated CD36 and reduced the uptake of free fatty acids in hepatocytes, thus achieving the inhibition of hepatic steatosis and liver injury." (PMID 39944639, 2025). "Thus, the obtained results show that the protective effect of the I3C against liver steatosis and reversed the decreased liver ILC1 induced by HFD in an AhR-dependent manner." (PMID 40046764, 2025). "Also, a I3C administration for 6 weeks improved liver steatosis and increased the frequency of liver ILC1 induced by HFD through aryl hydrocarbon receptor (AhR) activation." (PMID 40046764, 2025). "Additionally, hepatic AHR activation induces CD36 gene expression and increases fatty acid uptake, promoting hepatic steatosis." (PMID 39866414, 2025). "This study investigated the messenger RNA (mRNA) expression levels of four genes (AHR, FFAR2, FXR, and TGR5) in patients with COVID-19, stratified by the presence or absence of metabolic-associated fatty liver disease (MAFLD)." (PMID 38932276, 2024). "CD36, an AhR target gene that promotes FFA translocation into the liver, was reduced in HFD-fed CadKO females, suggesting a mechanism for protection from hepatic steatosis." (PMID 37443781, 2023). "An elegant study utilized hepatocyte-specific AhR knockout mouse model (AhR-hKO) and showed that the absence of AhR in hepatocytes accelerated high-fat diet induced hepatic steatosis, inflammation, and injury." (PMID 37284280, 2023). "In opposition to the notion that activated AhR exacerbates hallmarks of NAFLD and genetic or pharmacological inhibition of AhR protects against fatty liver disease, recent studies have indicated the hepatoprotective role of induced AhR signaling in NAFLD models." (PMID 37284280, 2023). "Combining the in vitro and in vivo results, AhR antagonist HBU651 may benefit chronic inflammatory diseases and peripheral inflammation, including hepatic steatosis and/or neuroinflammation, by blocking activation of macrophages, microglia, and astrocytes." (PMID 36499198, 2022).
Hepatic steatosis (continued). "In addition, a natural AhR agonist, Indigo, protects against HFD-induced insulin resistance, glucose dysregulation, and fatty liver disease in an HFD-induced animal model." (PMID 36418969, 2022). "In another study, a synthetic pelargonidin (Mt-P) proved to transactivate AHR and to attenuate body weight gain, intestinal and hepatic inflammation, and glucose intolerance, yet without alleviating liver steatosis in C57BL/6 mice on HFD supplemented with fructose." (PMID 40687891, 2025). "The activation of ERK promoted AHR expression, then AHR directly binded to the promoter regions of the key fatty acid oxidation enzymes ACOX 1 and CPT1A to transcribe and activate their expression and then achieved normal fatty acid oxidation function, thus inhibiting hepatic steatosis." (PMID 39944639, 2025). "The data from the high-fat diet fed control and inducible AhR knockout mice suggested that the inducible female knockout mice were resistant to weight gain and hepatic steatosis, whereas males were not protected from hepatotoxicity – clearly indicating a sexual dimorphism." (PMID 37284280, 2023). "Therefore, the authors suggest AHR and CD36 as novel therapeutic targets in fatty liver disease." (PMID 34075438, 2021). "Importantly, other pollutants that activate the AhR, such as 2,3,7,8-tetrachlorodibenzo-p-dioxin or PCB126, have previously been shown to exert similar metabolic effects as those observed here for methomyl, including hepatic steatosis and decreased body weights." (PMID 37623845, 2023).
atopic dermatitis (78 papers, 2014 to 2026). "In fact, specific disruption of AHR function in the skin has been found to be associated with the pathogenesis of various skin diseases, most prevalently atopic dermatitis (AD)." (PMID 35204110, 2022). "An obvious choice of target is the skin, which is affected by environmental pollutants linked to inflammatory diseases such as atopic dermatitis, pigmentation disorders or acne albeit the mechanistic details of AHR involvement remain unclear." (PMID 39242971, 2024). "Similarly, it is also reported that AhR improves the function of the skin barrier by activating the expression of filaggrin, and that there is a significant increase in dry skin phenotypes in atopic dermatitis patients with AhR polymorphism." (PMID 31216667, 2019). "Whether these potentially beneficial effects of coal tar will be limited to atopic dermatitis associated with filaggrin mutations or whether AHR activation may provide general benefit to this inflammatory skin disease is currently unknown." (PMID 24904982, 2014). "Also, RES has an anti-inflammatory role in atopic dermatitis, an inflammatory disease in which there is an alteration of the cytoplasmic aryl hydrocarbon receptor (AhR) pathway implicated in the regulation of the expression of several genes that influence skin inflammation." (PMID 40077707, 2025). "In the treatment of atopic dermatitis (AD), synergistic activation of the aryl hydrocarbon receptor (AHR)/nuclear factor erythroid 2-related factor 2 (NRF2) pathways represents a promising strategy." (PMID 42074173, 2026). "Recently, we demonstrated that a plant extract mixture consisting of apple, curly kale and green tea activates the AhR and shows beneficial effects in an atopic dermatitis skin model." (PMID 42050003, 2026). "In patients with atopic dermatitis, the protein levels in serum, mRNA in peripheral blood mononuclear cells, and tissue expression in skin lesions of AhR were all increased." (PMID 40508196, 2025). "In fact, it has been shown that altered AhR signaling is involved in the progression of atopic dermatitis, with impairment of its skin barrier function and increased immune activity." (PMID 40077707, 2025). "A topical medication for the treatment of plaque psoriasis and atopic dermatitis containing an AhR agonist is already on the market, whilst AhR is considered a promising target for chemoprevention." (PMID 39942795, 2025). "In atopic dermatitis, it was found that AHR signaling increased the expression of OVOL1, which after its passage to the nucleus increased Filaggrin." (PMID 38907248, 2024). "For the inflammatory skin diseases atopic dermatitis and psoriasis, a topical AhR agonist, Tapinarof, is already on the market." (PMID 38915403, 2024). "The aryl hydrocarbon receptor (AhR)-related signaling pathway has emerged as a promising target for alleviating the symptoms of atopic dermatitis (AD), a chronic inflammatory skin disease characterized by epidermal barrier dysfunction and immune dysregulation." (PMID 39770040, 2024). "A link between activation of the AhR and anti-inflammatory properties has already been established in atopic dermatitis and intestinal inflammation." (PMID 38915403, 2024). "AhR is a double-edged sword because it has two opposite effects on the skin: improving atopic dermatitis and worsening skin inflammation." (PMID 36983027, 2023). "The AhR‐modulating agent tapinarof (GSK2894512) is a promising naturally derived drug molecule for the treatment of atopic dermatitis (AD) and plaque psoriasis." (PMID 37382269, 2023). "Changes in AHR expression in immune cells of the circulating systems of patients have shown a direct correlation between AHR and cytokines in atopic dermatitis and morbid obesity." (PMID 37760608, 2023). "As a result, diosmin improves atopic dermatitis by restoring skin barrier function via the AhR signaling pathways." (PMID 36983027, 2023).